STARD7 (StAR related lipid transfer domain containing 7)
Description:
Mediates non-vesicular transfer of phosphatidylcholine to mitochondria, thereby maintaining mitochondrial membrane lipid composition, cristae organization, and respiratory function across diverse tissues. [StAR-related lipid transfer protein 7, mitochondrial]: Transfers phosphatidylcholine (PC) from the endoplasmic reticulum to the mitochondrial outer membrane at ER-mitochondria contact sites, thereby maintaining mitochondrial PC content, respiratory complex stability and mitochondrial cristae morphology. [StAR-related lipid transfer protein 7, mature]: Transfers phosphatidylcholine (PC) between the mitochondrial outer and inner membranes, contributing to mitochondrial lipid homeostasis. The mature cytosolic and intermembrane space forms of STARD7 mediate non-vesicular PC transport by transiently associating with mitochondrial membranes. Required for normal cristae architecture and optimal activity of the respiratory chain. Mediates intracellular distribution of coenzyme Q (ubiquinone), the intermembrane space form supports mitochondrial coenzyme Q biosynthesis and the cytosolic form transfers coenzyme Q to extramitochondrial membranes, enhancing antioxidant protection and limiting ferroptosis sensitivity.
Synonyms: GTT1; ADCME; BAFME2; FAME; FAME2; FCMTE2
Tractability: Antibody: its Gene Ontology location is reachable by antibodies, with medium confidence. PROTAC: ubiquitination databases record sites on it; its protein half-life has been measured.
Gene: Protein-coding gene on chromosome 2 (96,184,859 to 96,208,849, reverse strand). Ensembl gene ENSG00000084090.
Subcellular location: Mitochondrion outer membrane (StAR-related lipid transfer protein 7, mitochondrial); Mitochondrion intermembrane space (StAR-related lipid transfer protein 7, mature); Cytoplasm, cytosol
Subcellular location (Human Protein Atlas): Mitochondria
Pathways (Reactome):
Metabolism: Synthesis of PC; Ubiquinol biosynthesis
Metabolism of proteins: Mitochondrial protein degradation
Gene Ontology:
Molecular function: phosphatidylcholine transfer activity; protein binding; lipid transfer activity; lipid binding; molecular carrier activity
Biological process: intermembrane phospholipid transfer; mitochondrial membrane organization; regulation of cellular respiration; phosphatidylcholine biosynthetic process; ubiquinone biosynthetic process
Cellular component: cytosol; mitochondrial intermembrane space; mitochondrial outer membrane; mitochondrion; cytoplasm
Genetic constraint (gnomAD): Loss-of-function variants: 26 observed, 37.78 expected, observed/expected ratio (o/e) 0.69, 90% interval 0.5 to 0.95. The upper end of that interval is the gene's LOEUF score, 0.95, which puts it in group 4 of 6, group 1 being the genes least tolerant of losing a copy. Missense variants: 490 observed, 480.96 expected, observed/expected ratio (o/e) 1.02, 90% interval 0.94 to 1.1. Synonymous variants: 198 observed, 178.03 expected, observed/expected ratio (o/e) 1.11, 90% interval 0.99 to 1.25.
Homologues: Orthologues: chimpanzee STARD7 (99% identical), macaque STARD7 (98% identical), dog STARD7 (95% identical), pig STARD7 (94% identical), rabbit STARD7 (94% identical), rat Stard7 (92% identical), mouse Stard7 (92% identical), guinea pig STARD7 (92% identical), tropical clawed frog stard7 (58% identical), zebrafish stard7 (58% identical), Caenorhabditis elegans C06H2.2 (30% identical), Drosophila melanogaster CG6565 (28% identical). Paralogues in human: PCTP (16% identical), STARD10 (14% identical).
Diseases named in the same sentence as STARD7 in open-access papers:
STARD7 is named in the same sentence as 42 diseases in open-access papers, as found by Europe PMC text mining. Sharing a sentence is not in itself a finding about the gene and the disease. The quoted sentences say what the papers report.
epilepsy (5 papers, 2010 to 2025). A brain disorder characterized by episodes of abnormally increased neuronal discharge resulting in transient episodes of sensory or motor neurological dysfunction, or psychic dysfunction. "This mitochondrial fragmentation phenotype is similar to reduction in PCs through loss of the PC transfer protein STARD7, which causes mitochondrial disfunction associated with a seizure disorder in humans." (PMID 40027629, 2025). "Moreover, loss of STARD7, which causes mitochondrial dysfunction associated with a seizure disorder in humans, has been shown to alter mitochondrial morphology with increased blebbing and loss of cristae structure in mammalian cells." (PMID 41325461, 2025). "However, in all reports of STARD7-related epilepsy, all cases are due to the expansion of the 5 bp repeat in intron 1, and other STARD7 pathogenic variants have never been reported in patients." (PMID 36186435, 2022). "STARD7 pathogenic variants cause an autosomal dominant familial adult myoclonic epilepsy (MIM: #607876), which is characterized as epilepsy that can occur as early as puberty, but no other central nervous systemic abnormality or phenotype have been reported in infancy." (PMID 36186435, 2022).
hydatidiform mole (2 papers, 2012 to 2013). A gestational trophoblastic disorder characterized by marked enlargement of the chorionic villi, hyperplasia of the villous trophoblastic cells and hydropic changes. "First, StarD7 was originally found to be upregulated in the choriocarcinoma JEG-3 cell line as compared with the nonmalignant counterpart, complete hydatidiform mole, and normal trophoblastic tissue." (PMID 23507753, 2013). "First, StarD7 was originally identified as an up-regulated gene in the choriocarcinoma JEG-3 cell line with respect to their nonmalignant counterpart, complete hydatidiform mole and normal trophoblastic tissue." (PMID 22952907, 2012).
placental disorders (2 papers, 2012 to 2022). "Therefore, dysregulation of StarD7 expression could result in an altered trophoblast function or differentiation leading to an increased risk of placental disorders." (PMID 22952907, 2012). "Indeed, recurrent early pregnancy loss risk was linked with a decreased Cx43 transcript and protein expression in trophoblast cells, highlighting the necessity to explore the StarD7 role in placental disorders." (PMID 36584213, 2022).
atopic dermatitis (1 paper, 2022). "It has been reported that StarD7 haploinsufficient mice present alterations in lung epithelial barrier function with an enhanced allergic response, spontaneous atopic dermatitis, and decreased amount of the key tight junction protein zonula occludens-1 (ZO-1)." (PMID 36584213, 2022).
benign breast neoplasms (1 paper, 2025). "Interestingly, mRNA levels of STARD7 were found elevated in benign breast neoplasms as well as in both ductal and invasive carcinomas when compared to levels in normal breast, suggesting that STARD7 overexpression occurs early during tumor development." (PMID 40443279, 2025). "STARD7 transcripts were indeed enriched in breast tumors versus normal adjacent tissues." (PMID 40443279, 2025).
breast carcinoma (1 paper, 2025). "Loss of STARD7 in breast cancer cells causes a metabolic reprogramming characterized by the accumulation of several mitochondrial metabolites, including carnitine derivatives and S‐Adenosylmethionine (SAM)." (PMID 40443279, 2025). "Collectively, these data indicate that ciliogenesis occurs in breast cancer cells undergoing autophagy, a process seen upon STARD7 deficiency." (PMID 40443279, 2025). "Of note, the ER stress inducer RNA‐dependent protein kinase (PKR)‐like ER kinase (PERK), which is enriched in MAMs, was found elevated upon STARD7 deficiency in all tested breast cancer cell lines, especially in MDA‐MB231 cells." (PMID 40443279, 2025). "Here, the loss of STARD7, a lipid transfer protein whose expression is enhanced in breast cancer, is shown to lead a metabolic reprogramming characterized by the accumulation of carnitine derivatives and S‐Adenosyl‐L‐methionine (SAM)." (PMID 40443279, 2025). "To prove that the ciliogenesis signature seen upon STARD7 deficiency in breast cancer cells results from autophagy, we next quantified mRNA levels of candidates involved in ciliogenesis in MCF7 cells treated with the mTORC1 inhibitor Rapamycin." (PMID 40443279, 2025). "Therefore, loss of STARD7 leads to higher numbers of mitochondria‐associated membranes (MAMs) in breast cancer cells, potentially as a compensatory mechanism of a defective PC transport between both organelles." (PMID 40443279, 2025). "Therefore, the stimulation of breast cancer cells with SAM remarkably mimics molecular changes seen upon STARD7 deficiency, which suggests that STARD7, as a lipid transfer protein, promotes cell cycle progression mainly by limiting SAM levels in breast cancer cells." (PMID 40443279, 2025). "We systematically detected high STARD7 protein levels in all tested breast cancer cell lines, although at lower levels in both MCF10A and T47D cell lines." (PMID 40443279, 2025). "As an additional evidence linking STARD7 expression to DNA replication in breast cancer cells, levels of candidates involved in kinetochore formation were downregulated in MCF7 or T47D breast cells lacking STARD7." (PMID 40443279, 2025). "To learn more on gene candidates whose expression is regulated by STARD7, we next established the transcriptomic signature of control versus STARD7‐depleted breast cancer cells by RNA sequencing experiments." (PMID 40443279, 2025). "Their mitochondria rely on the transfer of phosphatidylcholine from the endoplasmic reticulum to their membranes by STARD7, a candidate upregulated in breast cancer, to be functional." (PMID 40443279, 2025). "To define the biological processes controlled by STARD7 in breast cancer, we first assessed STARD7 expression in a variety of human breast cancer cell lines using the DepMap dataset." (PMID 40443279, 2025). "Therefore, STARD7 supports DNA replication, at least by promoting kinetochore assembly in breast cancer cells." (PMID 40443279, 2025). "Likewise, Luminal A‐ and Luminal B‐derived breast cancer cell lines also showed comparable mRNA levels of STARD7." (PMID 40443279, 2025). "We next assessed STARD7 protein levels in several established breast cancer cell lines." (PMID 40443279, 2025). "STARD7 expression was also found to be enriched in the basal subtype of breast cancer." (PMID 40443279, 2025). "Interestingly data from single‐cell RNA analyses carried out on human breast cancers indicated that STARD7 expression was detected in multiple cell types, especially in cycling and transformed breast epithelial cells." (PMID 40443279, 2025). "Therefore, our data demonstrate that breast cancer cells of any subtype (ERα+ tumors and TNBCs) overexpress STARD7 to support cell proliferation." (PMID 40443279, 2025). "Accumulation of SAMs is an important feature of STARD7‐depleted breast cancer cells." (PMID 40443279, 2025). "Therefore, mitochondria rely on STARD7 to support cell cycle progression in breast cancer." (PMID 40443279, 2025).
breast carcinoma (continued). "Therefore, breast cancer development is characterized by elevated levels of STARD7." (PMID 40443279, 2025). "Therefore, STARD7 promotes ERα signaling in breast cancer cells." (PMID 40443279, 2025). "In conclusion, our study defines STARD7 as a candidate that promotes cell proliferation as well as both ERα‐ and EGFR‐dependent signaling cascades in breast cancer." (PMID 40443279, 2025). "We found that STARD7 mRNA levels were comparable in TNBCs, ERα+ and ERBB2+ breast cancer cell lines." (PMID 40443279, 2025). "Carnitine palmitoyltransferases, which shuttle acylcarnitines between mitochondrial membranes, are properly expressed in breast cancer cells lacking STARD7 (data not shown)." (PMID 40443279, 2025). "As a result, both NUF2 and TXNIP protein levels were downregulated in breast cancer cells lacking STARD7." (PMID 40443279, 2025). "It is worth mentioning that levels of ACC, which produces malonyl‐CoA, an inhibitor of FA oxidation, are downregulated in breast cancer cells lacking STARD7." (PMID 40443279, 2025). "As a result, breast cancer cells lacking STARD7 undergo cell cycle arrest and do not properly signal through both ERα and EGFR." (PMID 40443279, 2025). "Accumulation of SAMs in breast cancer cells lacking STARD7 enhances H3K27 methylation on genes coding for candidates involved in cell cycle progression." (PMID 40443279, 2025). "An enrichment overview of these signatures revealed numerous deregulated metabolic pathways in breast cancer cells lacking STARD7." (PMID 40443279, 2025). "Moreover, levels of Thioredoxin reductase (TRXR1), which plays a key role in protection against oxidant injury, were increased in breast cancer cells lacking STARD7." (PMID 40443279, 2025). "Given the fact that the ER stress inducer PERK was more expressed in breast cancer cells lacking STARD7, we also look at levels of other ER stress downstream targets such as Eukaryotic Initiation Factor 2α (EIF2α), X box‐binding protein 1 (XBP1) and Activating transcription factor 4 (ATF4)." (PMID 40443279, 2025). "Yet, underlying molecular mechanisms involved in the increase of MAMs in breast cancer cells lacking STARD7 are currently unknown." (PMID 40443279, 2025). "Therefore, phenotypic alterations found in breast cancer cells lacking STARD7 result from multiple molecular mechanisms, including a defective PC transport and possibly destabilization of important mitochondrial proteins." (PMID 40443279, 2025). "Breast cancer cells lacking STARD7 also showed elevated levels of LAMP1 or LAMP2, which, together with flow cytometry analyses using Lysotracker, demonstrates that STARD7 deficiency in both MCF7 and MDA‐MB231 but not in T47D cells led to an increased in lysosomal biomass, a hallmark of autophagy." (PMID 40443279, 2025). "The enhanced mitochondria‐ER contact sites seen in breast cancer cells lacking STARD7 may be a compensatory mechanism to support lipid transfer." (PMID 40443279, 2025). "Breast cancer cells lacking STARD7 do not have enough PC in mitochondria and may therefore try to synthetize PC from Phosphatidylethanolamine (PE) through a cascade of reactions relying on Phosphatidylethanolamine N‐Methyl Transferase (PEMT) and on SAM." (PMID 40443279, 2025). "Fatty acids (FA) β‐oxidation was strongly upregulated in breast cancer cell lacking STARD7." (PMID 40443279, 2025). "Breast cancer cells lacking STARD7 show a profound modification of mitochondrial ultrastructure." (PMID 40443279, 2025). "Therefore, a metabolic reprogramming occurs in breast cancer cells lacking STARD7." (PMID 40443279, 2025). "Interestingly, levels of the voltage‐dependent anion channel VDAC are dramatically decreased in MAMs and this could be seen as a pro‐survival adaptation in breast cancer cells lacking STARD7." (PMID 40443279, 2025). "It is currently unknown why breast cancer cells lacking STARD7 accumulate SAMs." (PMID 40443279, 2025).
breast carcinoma (continued). "To assess STARD7 biological functions in breast cancer, we first generated MCF7 cells lacking STARD7." (PMID 40443279, 2025).
Chronic colitis (1 paper, 2024). A chronic inflammatory disease of the large intestine (colon, cecum and rectum). "Utilizing STARD7-deficient (Stard7+/–) mice and employing the DSS-induced and Il10–/– spontaneous model of colitis, we found that STARD7 deficiency exacerbated the development of acute and chronic colitis." (PMID 39576011, 2024).
colitis (1 paper, 2024). Inflammation of the colon. "STARD7 haploinsufficiency in mice was associated with increased susceptibility to innate immune cell– and T cell–dependent colitis." (PMID 39576011, 2024). "DSS treatment of Stard7+/– mice led to an exaggerated colitis phenotype, including increased loss of body weight, colon shortening, and histopathological changes to the colon, including severe transmural infiltration and epithelial destruction." (PMID 39576011, 2024). "The aim of this study was to define the contribution of STARD7 in the regulation of the intestinal epithelial mitochondrial function and susceptibility to colitis." (PMID 39576011, 2024). "STARD7 deficiency increased susceptibility to both innate immune cell– and T cell–dependent colitis." (PMID 39576011, 2024). "Together, these data show that mice with diminished STARD7 expression have increased susceptibility to development of both innate and T cell–dependent colitis and that metformin treatment can abrogate the exaggerated colitis phenotype." (PMID 39576011, 2024). "Together, these data show that mice deficient in STARD7 have increased susceptibility to development of both innate and T cell–dependent colitis." (PMID 39576011, 2024). "Stard7+/–Il10–/– mice exhibited more severe symptoms of colitis and demonstrated exaggerated weight loss before they reached 5–6 weeks of age, indicating that the STARD7 deficiency was associated with early-onset colitis development." (PMID 39576011, 2024). "Pretreatment of Stard7+/– mice with metformin significantly delayed the onset of DSS-induced colitis, as evidenced by delayed development of clinical symptoms and diminished weight loss." (PMID 39576011, 2024). "We show that reconstitution of mitochondrial activity by AMP kinase (AMPK) activation in human intestinal cells led to improved barrier integrity and that treatment of Stard7+/– with an AMPK agonist demonstrated protection from the colitis phenotype in mice." (PMID 39576011, 2024). "Stard7+/– mice were more susceptible to the development of DSS-induced and Il10–/– spontaneous models of colitis." (PMID 39576011, 2024). "Next, we tested the role of STARD7 in the innate immune cell–driven colitis phenotype." (PMID 39576011, 2024). "Next, we interrogated the role of STARD7 in the T cell–driven colitis phenotype." (PMID 39576011, 2024). "Stard7+/– mice were mated with Il10–/– mice on C57BL/6 background and monitored for the development of the spontaneous colitis phenotype." (PMID 39576011, 2024). "To test whether metformin could abrogate the exaggerated colitis phenotype observed in Stard7+/– mice, we pretreated Stard7+/– mice with metformin and examined DSS-induced colitis outcomes." (PMID 39576011, 2024).
colon cancer (1 paper, 2023). "We also deleted PARL and STARD7 in the colon cancer cell line HCT116." (PMID 36658222, 2023).
developmental and epileptic encephalopathy (1 paper, 2022). An epilepsy associated with developmental impairment that may be due to either the underlying etiology or the superimposed epileptic activity, or both. "Thirteen genes were found disrupted, in which the CACNA1E (in case 12) and STARD7 (in case 17) genes are associated with the developmental and epileptic encephalopathy (MIM: #618285) and the familial adult myoclonic epilepsy (MIM: #607876), respectively." (PMID 36186435, 2022).
hepatoma (1 paper, 2013). "Semiquantitative RT-PCR assays in a series of tumor cell lines have shown that StarD7 has widespread expression, predominantly in trophoblast-derived JEG-3, JAR, and HTR8-SVneo cells, hepatocellular carcinoma HepG2 cells, and colorectal adenocarcinoma HT29 and Caco-2 cells." (PMID 23507753, 2013).
infiltrating ductal carcinomas (1 paper, 2025). "STARD7 overexpression was also detected at the protein level in all our tested clinical cases of TNBCs as well as in most ER+ tumors (infiltrating ductal carcinomas)." (PMID 40443279, 2025).
intestinal cancer (1 paper, 2026). "The role of phosphatidylcholine transporters such as Stard7 in intestinal cancer development is unknown." (PMID 41912870, 2026).
intestinal tumor (1 paper, 2026). "Collectively, our results suggest that the genetic status critically controls the effects of Stard7 deficiency on intestinal tumor development." (PMID 41912870, 2026).
Mitochondrial myopathy (1 paper, 2020). "Mitochondrial myopathy due to StarD7 mutation in human has not been reported to date." (PMID 32071354, 2020).